E2F2 (E2F transcription factor 2)
Diseases named in the same sentence as E2F2 in open-access papers (continued):
Sharing a sentence is not in itself a finding about the gene and the disease.
colorectal cancer (13 papers, 2016 to 2025). A primary or metastatic malignant neoplasm that affects the colon or rectum. "Recently, we have demonstrated that E2F2 associate with B-Myb, and more intriguingly both transcription factors mutually regulate each other, thus forming an exquisite reciprocal feed-forward loop which plays a vital role in accelerating colorectal cancer progression." (PMID 35844795, 2022). "E2F2 is essential for B-Myb-induced malignant phenotype, and show positively correlation with B-Myb, interacting in colorectal cancer cells to activate ERK and AKT signaling pathways to promote carcinogenesis." (PMID 36855119, 2023). "Furtherly, we explored the differentially expressed level of E2F2 in different cancer types using Oncomine database, which revealed that E2F2 mRNA expression was downregulated in colorectal cancer among three significant unique analyses." (PMID 35069909, 2022). "Taken together, our data clarified a critical role for B-Myb in colorectal cancer and unraveled an exquisite mutual collaboration and reciprocal cross regulation between B-Myb and E2F2 that contribute to the malignant progression of human colorectal cancer." (PMID 34316028, 2021). "Although E2F2 has been well studied in multiple cancer types, it remains unclear in colorectal cancer." (PMID 35069909, 2022). "Consistently, our recent study demonstrated that compared with E2F1 and E2F3, E2F2 might specifically play a pivotal role in colorectal cancer and serve as a specific therapeutic target." (PMID 35844795, 2022). "Growing evidence has revealed that the E2F family of transcription factor 2 (E2F2) participates in the tumorigenesis and progression of various tumors, but its role in colorectal cancer (CRC) remains largely unknown." (PMID 35069909, 2022). "Notably, B-Myb and E2F2 exhibited positive expression correlation, and interacted with each other in colorectal cancer cells." (PMID 34316028, 2021). "In this work, we investigated one of these possible mechanisms, showing that E2F2 could have a role not only in being a direct effector of miR-31 in the regulation of the colorectal cancer proliferation, but also in the resistance to treatment with anti-EGFR." (PMID 32164324, 2020). "In addition, the expression of E2F2, a transcription factor identified as a direct target of miR-31 in colorectal cancer, increased by 4-fold after transfection of HCT116 cell line with anti-miR-31-3p in comparison to the NC." (PMID 32164324, 2020). "To identify the molecular mechanism underlying the ETV4-mediated EMT and metastasis in colorectal cancer cells, we next leveraged our RNA-seq data and a series of key downstream genes associated with EMT were further confirmed, including MER3, MSX1, LOXL2, THRB, WISP2, COL11A1, ADRB2 and E2F2." (PMID 41281746, 2025). "Moreover, both B-Myb and E2F2 are required for the activation of ERK and AKT signaling pathways in colorectal cancer cells." (PMID 34316028, 2021).
glioblastoma (12 papers, 2014 to 2025). The most malignant astrocytic tumor (WHO grade IV). "As expression of the E2F2 gene is associated with glioblastoma stem cells and is involved in the transformation of human astrocytes, the present findings suggest that E2F2 is involved in gliomagenesis and could be explored as a potential therapeutic target in malignant gliomas." (PMID 25202354, 2014). "Collectively, these data uncover a crucial role for microRNAs-E2F2 pathway in controlling the development of glioblastoma." (PMID 38807594, 2024). "Elevated Let-7b also repressed E2F2 expression in glioblastoma CSCs, resulting in reductions in tumorsphere growth and CSC populations." (PMID 34476219, 2021). "Specifically, we found that three E2F members showed decreased expression upon radiation: E2F1, E2F2, and E2F8, all of which have been previously implicated in glioblastoma development." (PMID 32488114, 2020). "In a previous genome-wide expression profiling study, we identified E2F2 as a hyperexpressed gene in stem-like cells of distinct glioblastoma multiforme (GBM) specimens." (PMID 25202354, 2014). "Abnormal expression and activity of E2F2 have been observed in glioblastoma cells, suggesting that it may contribute to the development and progression of the disease." (PMID 38807594, 2024). "Other studies have also suggested that E2F2 mediates the radioresistance of glioblastoma CSCs." (PMID 34476219, 2021). "RNAi-mediated E2F-2 knockdown inhibited human glioblastoma cell tumorigenicity." (PMID 28558060, 2017). "E2F2 has been implicated in regulation of cancer stem cell (CSC) properties by various microRNAs and necessary for self-renewal of stem cells and radioresistance of glioblastoma, whereas E2F8 is thought to be associated with tumorigenesis and radioresistance as well as with EMT." (PMID 40316727, 2025). "Furthermore, by directly targeting E2F2, miR-125b could regulate the proliferation and miR-218 could inhibit the growth and metabolism of human glioblastoma cells." (PMID 38807594, 2024). "Research has shown that E2F2 may play a role in glioblastoma." (PMID 38807594, 2024). "RNAi-mediated knockdown of E2F2 could inhibit tumorigenicity of human glioblastoma cells." (PMID 38807594, 2024). "In a recent study to evaluate early changes in expression in glioblastoma cells after radiation, we determined that down-regulation of genes implicated in the cell cycle, DNA repair and DNA replication is likely the result of decreased expression of FOXM1, E2F1, E2F2 and E2F8." (PMID 33804958, 2021). "E2F2 is required for the link NAD+ metabolism and the self-renewal transcriptional program in glioblastoma CSCs." (PMID 34476219, 2021). "Based on what is known regarding the regulation of E2F transcription factors, we decided to test if the previously identified Msi1 direct targets CDK6, CDKN1A/p21, CDKN1B/p27 affect E2F2 and E2F8 levels in glioblastoma cells." (PMID 33804958, 2021). "NAMPT is the rate-limiting enzyme in the NAD salvage pathway, and E2F2 acts downstream of NAMPT and controls ID1 gene transcription to drive glioblastoma CSC self-renewal." (PMID 34476219, 2021).
colon cancer (11 papers, 2017 to 2024). "On the one hand, studies have indicated that the expression of E2F2 was significantly elevated in colon cancer tissues compared to normal colon tissues, implicating E2F2 as a potential diagnostic biomarker for CRC." (PMID 38807594, 2024). "We also disclosed that E2F2 expression was significantly correlated with tumor stage in patients with colon cancer." (PMID 32117628, 2020). "Our analysis unveiled that the mRNA and protein expression levels of E2F2 were significantly higher in colon cancer tissues." (PMID 32117628, 2020). "PPAR-γ ligands were previously reported to inhibit the mRNA expressions of cyclin E and E2F2 in a colon cancer cell line." (PMID 28052030, 2017). "Troglitazone, which is a strong activator of PPAR-γ, was previously reported to inhibit the mRNA levels of cyclin E and E2F2 in a colon cancer cell line." (PMID 28052030, 2017). "The validity of these findings was further reinforced by the results showing that three additional UPR inducers, specifically tunicamycin, A23187, and Brefeldin-A, led to significant inhibition of FBXO5 and E2F2 expression in multiple colon cancer cell lines, including HT29, HCT116, and SW480." (PMID 38212299, 2024). "On the other hand, E2F2 can also have a function as a suppressor in colon cancer." (PMID 36551770, 2022). "In fact, the expression level of E2F2 was very low level in colon cancer and E2F2 inhibition could enhance proliferation and cell cycle of colon cancer cells by suppressing the expression of surviving and regulating the expression of C-MYC, CCNA2, MCM4 as well as CDK2." (PMID 32117628, 2020). "Our study implied that E2F3, E2F4, E2F7 and E2F8 are potential targets of precision therapy for patients with colon cancer while E2F1, E2F2, E3F3, E2F5, E2F7 and E2F8 are potential biomarkers for the diagnosis of colon cancer." (PMID 32117628, 2020). "The isoform miR-31-P targets and represses DICER by translational repression, whereas miR-31-M targets and represses CSBPα, STK40 and E2F2, in HCT116 colon cancer cells, suggesting that specific genes regulated by miR-31 might be isoform dependent." (PMID 34716428, 2022). "Our studies indicated that the deregulation of E2F1, E2F2, E2F3, E2F5, E2F7 and E2F8 in colon cancer tissues might play a vital role in colon cancer oncogenesis, which could be promising diagnostic biomarkers for LUAD." (PMID 32117628, 2020).
pancreatic cancer (11 papers, 2014 to 2025). "Elevated E2F2 expression promotes proliferation and confers gemcitabine resistance in pancreatic cancer and is also elevated in patients with RCC, suggesting its potential utility as a diagnostic biomarker." (PMID 41303409, 2025). "We found that mitosis-independent H3S28ph was localized to cells expressing E2F2 at a high level in mouse pancreatic tumors and that it contributed to E2F2 expression in stressed cells in vitro." (PMID 40316727, 2025). "Immunohistochemistry was performed for serial sections of pancreatic tumor tissue from the KPC orthotopic transplantation model with antibodies to E2F2, H3S28ph, LIN28B, and other markers whose gene expression was suppressed by BA in vitro." (PMID 40316727, 2025). "The LncRNA DNR/miR-214-5P/E2F2 axis functions as an oncogene during pancreatic cancer development and is a potential target for pancreatic cancer therapy." (PMID 38152068, 2023). "For example, Yang and colleagues proposed that exosomes from M2 macrophages promoted angiogenesis and tumor growth in pancreatic cancer in an E2F2-dependent manner." (PMID 35637794, 2022). "For example, in pancreatic cancer miR-17-5p enhance its proliferation by disrupting RBL2/E2F2-repressing complexes." (PMID 34778021, 2021). "And DANCR could promote pancreatic cancer cell growth and metastasis through working as a competing endogenous RNA (ceRNA) of miR-214-5p, and positively regulate E2F2 expression in pancreatic cancer cells." (PMID 33123287, 2020). "Yao and others demonstrated that miR-214-5p expression had a negative correlation with E2F2 expression in pancreatic cancer tissue samples." (PMID 37047293, 2023).
melanoma (9 papers, 2014 to 2025). A malignant, usually aggressive tumor composed of atypical, neoplastic melanocytes. "Knockdown of IFI6 increased the sensitivity of NRAS-mutant melanoma to DNA replication stress-inducing agents, and simultaneous loss of E2F2 and IFI6 rescues this effect." (PMID 27608486, 2016). "IFI6 has also been shown to mediate mutated N-Ras-induced transformation and melanoma growth, and the knockdown of IFI6 resulted in DNA replication stress due to dysregulated DNA replication via E2F2, resulting in senescence or apoptosis." (PMID 37686559, 2023). "In melanoma cells and primary human melanocytes, IFI6 loss results in the induction of cellular senescence as a result of E2F2-mediated dysregulated DNA replication and consequent DNA damage." (PMID 27608486, 2016). "Collectively, we demonstrate that IFI6, via E2F2 regulates DNA replication and melanoma development and growth, and this pathway can be pharmacologically targeted to inhibit NRAS-mutant melanoma." (PMID 27608486, 2016). "Further studies revealed that the introduction of NRASQ61K in primary human melanocytes increased IFI6 expression and downregulated E2F2 and several E2F2 target genes, similar to melanoma cells." (PMID 27608486, 2016). "Taken together, our results identify a new role for IFI6 in E2F2-mediated regulation of DNA replication and melanoma development and growth." (PMID 27608486, 2016). "Next, we asked if the E2F2 upregulation that results from IFI6 knockdown is necessary for melanoma growth inhibition." (PMID 27608486, 2016). "Further, treatment of GSPs also reduced the levels of pRbThr356, E2F1 and E2F2 proteins in melanoma cells which are the downstream targets of p21/WAF1/Cip1, and this effect of GSPs was dose-dependent." (PMID 25361006, 2014). "Based on these results, we tested whether immortalized melanocytes expressing NRASQ61K behaved similarly to the NRAS-mutant melanoma cells and primary human melanocytes that show regulation of E2F2 and its target genes." (PMID 27608486, 2016). "Based on these findings, we hypothesized that the loss of IFI6 results in dysregulated DNA replication via E2F2 upregulation, which in turn blocks NRAS-mutant melanoma tumor growth and melanomagenesis." (PMID 27608486, 2016). "We did not observe similar changes in mRNA levels of E2F2 or its target genes after IFI6 knockdown in BRAF-mutant or NF1-deficient melanoma cell lines." (PMID 27608486, 2016). "Notably, knockdown of IFI6 in BRAF-mutant, NF1-deficient, or triple wild-type melanoma did not alter the expression of E2F2 or its target genes." (PMID 27608486, 2016). "The expression levels of E2F2, E2F7, and E2F8 in the C4 melanoma cell subgroup were significantly higher compared to other subgroups." (PMID 39781353, 2025). "Among these genes, E2F2 and PDGFRB were widely recognized as key genes that impact melanoma secretion." (PMID 30214427, 2018). "To determine this, we simultaneously knocked down the expression of E2F2 and IFI6 using shRNA and observed a significant rescue of the NRAS-mutant melanoma cell's ability to form colonies in soft agar and tumors in mice." (PMID 27608486, 2016). "We also evaluated senescence markers in this scenario and found that simultaneous knockdown of E2F2 and IFI6 prevented IFI6-induced senescence in melanoma cells." (PMID 27608486, 2016). "Furthermore, simultaneous knockdown of E2F2 and IFI6 in melanoma cells resulted in a lower percentage of cells in S phase and normalized DNA replication compared with cells expressing IFI6 shRNA." (PMID 27608486, 2016).
melanoma (continued). "Thus, the ability of IFI6 to regulate DNA replication stress originates in its ability to repress E2F2 and its target genes specifically in the context of NRAS-mutant melanoma." (PMID 27608486, 2016).
retinoblastoma (8 papers, 2014 to 2024). A malignant tumor that originates in the nuclear layer of the retina. "Circcul2 inhibits the proliferation, invasion, and migration of retinoblastoma cells by regulating the miR-214-5P /E2F2 axis." (PMID 38152068, 2023). "A series of canonical pathways, including those involved in Rb (Retinoblastoma)/E2F cell cycle (Rb, E2f2, E2f3, E2f5, Cdk6, DHFR), Notch (Dll1, Notch 2, Jag1), Wnt (Wnt, Axin2, Wisp2/Ccn5) and NF-κB (Ikbip) were found to participate in this network." (PMID 30742662, 2019). "In RB1-mutated retinoblastoma, all three activating E2Fs were significantly upregulated: E2F1 (FC = 1.86, P = 2.56E-03), E2F2 (FC = 2.84, P = 2.31E-04), and E2F3 (FC = 3.72, P = 2.18E-10)." (PMID 25161863, 2014). "To determine which E2F transcription factors could be associated with upregulation of FA genes, we studied also the mRNA expression levels of activating E2F genes (E2F1, E2F2, E2F3) in RB1-mutated retinoblastoma and in basal breast tumors." (PMID 25161863, 2014). "Moreover, circCUL2 suppresses retinoblastoma cells by regulating miR-214-5p/E2F2 axis." (PMID 36551770, 2022). "This is strengthened by the observation that the mRNAs for E2F1 and E2F2, cyclins A1, A2 and cyclins E1 and E2 as well as the mRNAs for the ribonucleotide synthase subunits RRM1 and RRM2 are high in retinoblastoma primary tumors." (PMID 38332874, 2024). "To elucidate how RB1 influences HK1 and E2F2 expression in the context of cancer, we overexpressed the wild-type RB1 in Rb null WERI-Rb1 retinoblastoma cells in vitro." (PMID 35626705, 2022). "RT-PCR analysis confirmed the microarray expression of the E2F transcription activator E2F2 to be significantly high in advanced Rb tumors, compared to non-advanced Rb tumors." (PMID 35626705, 2022). "RT-PCR validations further confirmed the expression pattern of E2F2 and HK1 in advanced and non-advanced Rb tumors." (PMID 35626705, 2022).
bladder cancer (7 papers, 2016 to 2025). "We also found that E2F transcription factor 1 (E2F1) and E2F transcription factor 2 (E2F2) are candidate downstream modulators regulated by KDM5B in bladder cancer and NSCLC." (PMID 30344945, 2018).
neuroblastoma (7 papers, 2014 to 2024). Neuroblastoma (NB) is the most common solid, extracranial childhood tumor. "Silencing DOT1L decreased the expression of OCD1 and E2F2 (two target genes of N‐Myc) and suppressed the growth of neuroblastoma cells." (PMID 39307938, 2024). "Suppression of JMJD6 resulted in decreased E2F2, N-Myc, and c-Myc gene expression, reduced neuroblastoma cell proliferation, induction of apoptosis in vitro, and inhibition of tumor growth in vivo." (PMID 31346162, 2019). "The data demonstrate that JMJD6 is important for E2F2 and Myc expression, neuroblastoma tumor progression, and mouse survival in vivo." (PMID 31346162, 2019). "By contrast, in neuroblastomas, E2F2 was shown to positively regulate MYCN transcription and thought to be required for full activity of MYCN expression in aggressive neuroblastomas usually associated with poor prognosis." (PMID 25202354, 2014). "E2F2 was associated with the overall survival of neuroblastoma in GSE85047 and E-MTAB-1781 datasets, but not in TARGET and GSE16476 datasets." (PMID 35764946, 2022). "As JMJD6 regulates Myc and E2F2 expression, we examined whether JMJD6 modulates neuroblastoma cell proliferation, survival, and clonogenic capacity." (PMID 31346162, 2019). "Moreover, E2F2 was correlated with the event free survival of neuroblastoma in GSE85047 and E-MTAB-1781 datasets, but not in TARGET and GSE16476 datasets." (PMID 35764946, 2022).